HMMR (hyaluronan mediated motility receptor)
Description:
Receptor for hyaluronic acid (HA) (By similarity). Involved in cell motility (By similarity). When hyaluronan binds to HMMR, the phosphorylation of a number of proteins, including PTK2/FAK1 occurs. May also be involved in cellular transformation and metastasis formation, and in regulating extracellular-regulated kinase (ERK) activity. May act as a regulator of adipogenisis (By similarity).
Synonyms: CD168; IHABP; RHAMM
Tractability: Antibody: its Gene Ontology location is reachable by antibodies, with high confidence; UniProt places it where antibodies can reach, with medium confidence. PROTAC: ubiquitination databases record sites on it; a small molecule that binds it is known.
Safety:
Unwanted effects reported when the protein is acted on. In parentheses: how it was acted on, where the effect was seen, and who reports it.
neutropenia (source: ClinPGx)
Gene: Protein-coding gene on chromosome 5 (163,460,203 to 163,491,945, forward strand). Ensembl gene ENSG00000072571.
Subcellular location: Cell surface; Cytoplasm; Cytoplasm, cytoskeleton, spindle
Subcellular location (Human Protein Atlas): Microtubules; Centrosome; Cytosol
Pathways (Reactome):
Metabolism: Hyaluronan degradation; Hyaluronan metabolism
Cell Cycle: AURKA Activation by TPX2
Gene Ontology:
Molecular function: protein binding; cargo receptor activity; hyaluronic acid binding
Biological process: carbohydrate derivative transport; hyaluronan catabolic process; receptor-mediated endocytosis
Cellular component: centrosome; cytoplasm; cytosol; membrane; microtubule cytoskeleton; spindle; cell surface; plasma membrane
Genetic constraint (gnomAD): Loss-of-function variants: 20 observed, 26.47 expected, observed/expected ratio (o/e) 0.76, 90% interval 0.53 to 1.1. The upper end of that interval is the gene's LOEUF score, 1.1, which puts it in group 4 of 6, group 1 being the genes least tolerant of losing a copy. Missense variants: 257 observed, 261.66 expected, observed/expected ratio (o/e) 0.98, 90% interval 0.89 to 1.09. Synonymous variants: 98 observed, 95.09 expected, observed/expected ratio (o/e) 1.03, 90% interval 0.87 to 1.22.
Homologues: Orthologues: chimpanzee HMMR (99% identical), macaque HMMR (95% identical), dog HMMR (86% identical), pig HMMR (85% identical), rabbit HMMR (82% identical), guinea pig HMMR (78% identical), mouse Hmmr (75% identical), rat Hmmr (75% identical), tropical clawed frog hmmr (46% identical), zebrafish hmmr (35% identical).
Diseases named in the same sentence as HMMR in open-access papers:
HMMR is named in the same sentence as 138 diseases in open-access papers, as found by Europe PMC text mining. Sharing a sentence is not in itself a finding about the gene and the disease. The quoted sentences say what the papers report.
breast carcinoma (71 papers, 2009 to 2025). "The hyaluronan-mediated motility receptor (RHAMM) has been reported to be a breast cancer susceptibility gene with tightly controlled expression in normal tissues but elevated expression in many tumors, contributing to tumorigenesis and metastasis." (PMID 37256184, 2023). "The cumulative evidence presented above suggested that HMMR overexpression increases BRCA1-associated breast cancer risk by further perturbing foundational process(es) that are altered in this type of cancer." (PMID 35393420, 2022). "HMMR, also known as RHAMM, is associated with neoplastic processes in multiple tumor types, and it is a breast cancer susceptibility gene." (PMID 34925311, 2021). "The expressions of KIF4A, RACGAP1, CKS2, SHCBP1, and HMMR were high in breast cancer, associated with poor OS and different breast cancer subclasses." (PMID 33959662, 2021). "The SUCCESSA trial showed that hyaluronan-mediated motility receptor (HMMR) gene single nucleotide polymorphisms (SNPs) are significant predictors of CIN in female patients with breast cancer who underwent FEC chemotherapy." (PMID 33299642, 2020). "HMMR has been implicated in the pathogenesis of tumors like breast cancer and inflammatory disorders like osteoarthritis." (PMID 29593529, 2018). "HMMR, a breast cancer susceptibility gene in BRCA1 mutation carriers, encodes a non-integral hyaluronan receptor that promotes breast cancer migration and invasion in concert with the integral hyaluronan receptor CD44." (PMID 29566768, 2018). "This approach was shown to link breast cancer susceptibility to centrosome dysfunction in tumours carrying BRCA1 mutations, and importantly identified the HMMR gene as a new breast cancer susceptibility gene." (PMID 19285540, 2009). "The effect of hyaluronan-mediated motility receptor (HMMR) expression in BRCA1-associated breast cancer risk remains unknown." (PMID 35393420, 2022). "The consequences of HMMR overexpression against a Brca1-mutant background expose the initial interplay of these alterations that may promote development of BRCA1-associated breast cancer." (PMID 35393420, 2022). "Elevated HMMR expression is always associated with poor prognosis in breast cancer." (PMID 36704516, 2022). "It has been found that high expression of HMMR is associated with multiple human malignancies, such as gastric cancer, breast cancer, prostate cancer, ovarian cancer, bladder cancer, with characteristics of promoting cancer progression and indicating poor prognosis in patients." (PMID 35036134, 2021). "Moreover, elevated HMMR expression associates with poor prognosis in a variety of cancers, such as breast cancer, colorectal cancer, stomach cancer, endometrial cancer, prostate cancer, and multiple myeloma." (PMID 32231069, 2020). "That is, the N-terminal domain of HMMR binds microtubules, encoded in part by exon 4, and the expression of a naturally occurring splice variant that lacks exon 4 (-exon 4) correlates with progression of multiple myeloma and breast cancers." (PMID 32231069, 2020). "HMMR is also involved in cell division and is implicated in myelomas and breast cancer." (PMID 26295306, 2015). "Similarly, elevated HMMR expression is associated with poor prognosis for BRCA1mut breast cancer." (PMID 34965417, 2021). "Indeed, immortal MDA-MB-231 breast cancer cells contain an A664 frameshift mutation (cDNA change c.1992_1993insA), and the expression of HMMR is greatly reduced in lysates from nocodazole-synchronized, G2/M phase lysates generated from MDA-MB-231 cells relative to MCF7 cells or MCF10A cells." (PMID 32231069, 2020). "Moreover, HMMR is a breast cancer susceptibility gene product." (PMID 32231069, 2020).
breast carcinoma (continued). "A five-gene SLE prognostic signature (RACGAP1, HMMR, TTK, TOP2A, and KIF15) effectively stratified breast cancer survival risk." (PMID 40567613, 2025). "Inhibiting HMMR expression through compounds targeting key signaling pathways, such as mTOR, presents innovative therapeutic avenues, particularly in breast cancer." (PMID 38576486, 2024). "This study explores the multifaceted function of hyaluronan-mediated motility receptor (HMMR) in breast cancer progression." (PMID 38576486, 2024). "The study further highlights compounds capable of inhibiting certain pathways, which, in turn, would inhibit the upregulation of HMMR in breast cancer." (PMID 38576486, 2024). "We have further tried to demonstrate how HMMR can be inhibited through certain compounds that are key regulators of important signaling pathways which aid in breast cancer progression." (PMID 38576486, 2024). "All these databases represented the significant overexpression of HMMR in breast cancer at all stages and levels, as compared to normal samples and its involvement and importance as a therapeutic target." (PMID 38576486, 2024). "HMMR was overexpressed in most carcinomas, including acute myeloid leukaemia, breast cancer, and lung cancer." (PMID 38633247, 2024). "Elevated HMMR expression triggered by inflammatory signals correlates with unfavorable prognosis in breast cancer and various other malignancies." (PMID 38576486, 2024). "In breast cancer, elevated HMMR activates AURKA and reduces ARPC2 localisation in the mitotic cell cortex, which correlates with micronucleation and the activation of cGAS-STING and non-canonical NF-κB signalling." (PMID 38633247, 2024). "One such commonality is the role of the Hyaluronan-Mediated Motility Receptor (HMMR) in breast cancer, pancreatic cancer, and lung adenocarcinomas." (PMID 36704516, 2022). "The level of HMMR expression mediated by the transgene was lower than that observed in MCF7 (ERα-positive) breast cancer cells." (PMID 35393420, 2022). "The overexpression of HMMR increases breast cancer-mutant tumorigenesis by modifying the cancer cell phenotype and TME." (PMID 36726984, 2022). "For validation in UALCAN, GEPIA, and KM, 5 core genes (KIF4A, RACGAP1, CKS2, SHCBP1, and HMMR) were found to highly expressed in breast cancer tissues with poor prognosis." (PMID 33959662, 2021). "It has been shown that upregulation of HMMR expression is related to the aggressive growth and low survival rate of various cancers, such as breast cancer, colorectal cancer, and gastric cancer." (PMID 34150630, 2021). "In the breast cancer model, we found upregulation of the membrane-associated factors, E-selectin, BST2, and HMMR, as well as the cytokine CCL7 only under mixture-culture conditions." (PMID 31963450, 2020). "HMMR (Hyaluronan Mediated Motility Receptor) is widely expressed in many types of tumors, including prostate and breast cancer, and various forms of leukemia." (PMID 31681575, 2019). "Among the predictions, the product of the hyaluronan-mediated motility receptor (HMMR) gene, RHAMM, was found to be biochemically and functionally linked to the breast cancer gene, early onset 1 gene product (BRCA1)." (PMID 25830658, 2015). "The interplay between BRCA1 and RHAMM is linked to breast cancer, both through BRCA1 gene mutations in familial breast cancer and low-penetrance genetic variation at the HMMR locus (encoding RHAMM) associated with sporadic breast cancer." (PMID 24278741, 2012). "Four showed centrosome amplification (KIAA0101, KIF14, KIF23 and HMMR) on the HeLa cell line and the breast cancer cell line Hs578T." (PMID 22956898, 2012). "We have investigated gene and protein interactions in a centrosome-cantered module, including BRCA1/BRCA1 and HMMR/RHAMM, across biological systems ranging from breast cancer risk estimates to cellular phenotypes and cytoskeletal structures." (PMID 22110403, 2011).
breast carcinoma (continued). "Xrhamm is the ortholog of a candidate low-penetrance breast cancer susceptibility gene product (RHAMM, HMMR gene) whose over-expression in tumors is associated with poor prognosis and early age at diagnosis." (PMID 22110403, 2011). "The investigation unveiled an upregulation and overexpression of HMMR across almost all tumor samples, including various breast cancer stages, such as individual cancer stages, histological subtypes, breast cancer sub-classes, TNBC subtypes, and those based on patient age." (PMID 38576486, 2024). "Therefore, recognizing HMMR as a promising therapeutic target, the study validates the overexpression of HMMR in breast cancer and various pan cancers and its correlation with certain proteins such as AURKA, TPX2, and CDK1 through online databases." (PMID 38576486, 2024). "The hyaluronan-mediated motility receptor (HMMR, also known as RHAMM) interacts with BRCA1 to regulate cell division and apicobasal polarization of mammary epithelial cells, and is a potential modifier of BRCA1-associated breast cancer risk." (PMID 35393420, 2022). "A prognostic SLEscore consisting of five SLE-related genes (RACGAP1, HMMR, TTK, TOP2A, and KIF15) could distribute patients with breast cancer into the high- and low-risk groups according to survival rates with good predictive ability (p < 0.05)." (PMID 36726984, 2022). "These five genes (KIF4A, RACGAP1, CKS2, SHCBP1, and HMMR) could be potential targets for therapy in breast cancer and prediction of prognosis on the basis of bioinformatical analysis." (PMID 33959662, 2021). "Furthermore, Hyaluronan Mediated Motility Receptor (HMMR), a low penetrance breast cancer susceptibility gene important for regulating apicobasal polarity, is upregulated in BRCA1-deficient tumors." (PMID 35008272, 2021). "Here, we report that the palbociclib treatment leads to a reduction of the expression of both GTSE1 and HMMR, suggesting that they may contribute to the reduced breast cancer cell migration." (PMID 28978043, 2017). "The product of the HMMR gene, RHAMM, interacts with BRCA1 in the control of mammary epithelial polarization and this function may be at the basis of a modification of breast cancer risk in BRCA1 mutation carriers." (PMID 25830658, 2015). "Our results also revealed that high HMMR mRNA and protein expression is associated with an adverse prognosis in B-ALL pediatric patients, which is in agreement with the findings of Tarullo, Beck, and Tzankov in breast cancer, lymphoma, and acute myeloid leukemia, respectively." (PMID 39859458, 2025). "Consequently, these findings imply that HMMR could play a pivotal role as a crucial oncogenic regulator, highlighting its potential as a promising target for the therapeutic intervention of breast carcinoma." (PMID 38576486, 2024). "Similarly, we expanded the breast cancer input layer with the hyaluronan-mediated motility receptor (HMMR) connected to FN1; the TGFBR connected to SNAI1 and SNAI2; the interLeukin 1 receptor type I (IL1R1) and the thyroid hormone receptor beta (THRB) connected to TRAF1 and MYC, respectively." (PMID 28775339, 2017). "Here, HMMR overexpression induces the activation of cGAS-STING and non-canonical NF-κB signalling, instigating an immune permissive environment for breast cancer development." (PMID 35393420, 2022). "The novel prognostic SLEscore with five key therapeutic targets (RACGAP1, HMMR, TTK, TOP2A, and KIF15) was developed for the management of breast cancer patients with SLE using the LASSO algorithm." (PMID 36726984, 2022). "Here, we review the well–regulated inflammatory and fibrogenic functions of HA polymers and two HA receptors—CD44 and RHAMM (HMMR)—in cutaneous wound repair and consider evidence that these functions also contribute to the progression of breast cancer." (PMID 34827550, 2021).
breast carcinoma (continued). "RHAMM/HMMR, which promotes migration and invasion of breast cancer lines, is also elevated in breast cancer, particularly at the invasive front of tumors and in tumor cell subsets." (PMID 26106384, 2015). "Breast cancer was predicted for all three DDTs using CTD data and for both parent DDTs using OMIM data (where the link for p,p ́-DDT is via a single protein, the hyaluronan-mediated motility receptor, p = 0.208)." (PMID 21846611, 2011). "In addtion, in models of breast cancer, sarcoma, and bladder cancer, YAP binds with Smad2/3 to activate different target genes such as neuronal growth regulator 1 (NEGR1), hyaluronan-mediated motility receptor (HMMR), and CTGF." (PMID 40673277, 2025). "Importantly, the four most important hub genes RRM2, HMMR, EZH2, and CCNB1 appeared to play a significant role in various types of cancer such as non‐small cell lung carcinoma (NSCLC), liver and breast cancer." (PMID 39118438, 2024). "Additionally, HMMR also interacted with CD44, another HA receptor characterized by forming complexes with ERK1/2, to exert its functions in breast cancer." (PMID 35036134, 2021). "Similarly to GTSE1, HMMR is regulated by both TEAD4 and E2F1 and has a critical role in breast cancer cell migration." (PMID 28978043, 2017). "We then found that HMMR expression is positively correlated with the “TNF signaling via NF-κB” and “KEGG cytosolic DNA sensing” pathways in human basal-like and/or claudin-low tumors, but not in the other major breast cancer subtypes." (PMID 35393420, 2022).
lung carcinoma (29 papers, 2015 to 2025). "HMMR (hyaluronan-mediated motility receptor) has been revealed to be associated with reduced overall survival in lung cancer patients." (PMID 35830566, 2022). "HMMR forms a complex with BRCA1 or BRCA2 together with other proteins, and high expression of HMMR was associated with poor survival in liver, pancreatic and lung cancer." (PMID 30785874, 2019). "Elevated expression of HMMR has been linked to various cancers, including breast and lung cancer." (PMID 38293522, 2024). "Frequent overexpression of HMMR has been observed in various solid tumours and is linked with malignant behaviours and poor prognosis, including bladder cancer, pancreatic cancer, liver cancer, lung cancer and PCa." (PMID 36750558, 2023). "In the present study, we have identified a post-transcriptional modification that regulate the increased expression of HMMR in patients with lung cancer." (PMID 39990663, 2025). "Although the oncogenic role of HMMR is yet fully understood, its exact mechanism and function in lung cancer are still unclear, highlighting the need for further research to gain deeper insights into this area." (PMID 39990663, 2025). "HA interacts with hyaluronan mediated motility receptor (RHAMM) and CD44, and the inhibition of either of these proteins causes lung cancer cells to switch to an epithelial phenotype." (PMID 38139154, 2023). "We further examined the upstream miRNAs that regulate HMMR expression in the progression of lung cancer." (PMID 35311097, 2022). "Hyaluronic acid (HA) can be preferentially detected in high-grade lung cancer mesenchyme, and hyaluronic acid-mediated motor factor receptor (HMMR) expression was correlated with the prognostic survival of LUAD patients." (PMID 34692489, 2021). "It has been reported that HMMR is overexpressed in numerous tumors, including lung carcinoma, glioblastoma, prostate adenocarcinoma, and leukemia 51-54." (PMID 33061798, 2020). "The interaction between SDC1 and HMMR, the hyaluronan-mediated motility receptor overregulated in lung cancer, is related to tumor cell motility and differentiation, as well as the pathological stage, T classification, lymph node metastasis, and distant metastasis." (PMID 39228892, 2024). "HMMR is also highly expressed in human multiple malignancies, such as gastric cancer and lung cancer, which may promote cancer progression and lower patient survival rate." (PMID 33187219, 2020). "The in vitro siRNA-mediated MALAT1 silencing resulted in impaired lung cancer cell motility by altering the expression levels of cell motility-related genes, such as HMMR at pre-mRNA transcriptional level and CTHRC1, CCT4 and ROD1 at post-transcriptional level." (PMID 28253859, 2017). "Currently, abundant studies indicate that HMMR plays multiple functional roles in regulating proliferation and metastasis, maintenance of stemness and chemotherapy resistance in various tumours, such as lung cancer, liver cancer, bladder cancer and gastric cancer." (PMID 36750558, 2023). "CENPF (Centromere protein F) is a gene related to chromosome segregation during mitosis that reduces overall survival in lung cancer and is a hub gene (AURKB, BUB1B, KIF2C, HMMR, CENPF, and CENPU) overexpressed in cancer patients." (PMID 36661515, 2023). "Experimentally, the expression of HMMR in LUAD and lung cancer cell lines was determined using immunohistochemistry and quantitative RT-PCR assays." (PMID 35311097, 2022). "The correlation of the four genes HMMR, PFKP, TCN1, and TK1 with tumor-infiltrating immune cells and the survival curve in lung cancer was shown." (PMID 35898471, 2022). "Hyaluronan-mediated motility receptor (HMMR) plays a pivotal role in cell proliferation in various cancers, including lung cancer." (PMID 35311097, 2022). "The interaction of HMMR with SLC7A11 activates ferroptosis, enhances the cytotoxic effect of CD8 +T cells, and regulates the tumor immune microenvironment, suggesting an interaction with SLC7A5 in lung cancer." (PMID 39228892, 2024).